RGS1 (regulator of G protein signaling 1)
Diseases named in the same sentence as RGS1 in open-access papers (continued):
Sharing a sentence is not in itself a finding about the gene and the disease.
tumor (continued). "However, RGS1 gene-silenced NCIN87-DR cell immunization obviously decreased tumor size of Xenograft mice compared to that of solely NCIN87-DR cell immunized Xenograft mice." (PMID 37529094, 2022). "However, RGS1 is a real oncogenic factor in tumor cells and is known to promote immune cell maturation." (PMID 35879796, 2022). "Additionally, RGS1 protein was upregulated significantly in tumor tissues in the immunohistochemistry verification." (PMID 34956194, 2021). "In addition, RGS1 protein, located at the cytoplasm and membrane, is enriched in tumor tissues compared with normal tissues according to the IHC staining in the HPA database and verification experiment, further verifying its pathogenicity." (PMID 34956194, 2021). "This analysis showed that genes representing T-cell activation and tumor-killing including Ifng, Vcam1, Rgs1, and Il2rb, had higher expression levels, whereas T-cell exhaustion genes such as Tim-3, Ccl3, Rgs2, and Cd6f3, had lower expression levels in Ogr1−/− mice than that in the WT mice." (PMID 34158625, 2021). "RGS1 expression increased more than 2-fold in nearly all normal tissue samples (N10: 17/20 patients; N20: 19/20; N45: 19/20) as well as in the majority of tumor tissue samples (T10: 12/20; T20: 15/19; T45: 14/20)." (PMID 26222051, 2015). "Thus, tumor thickness, mitotic rate, tumor vascularity, RGS1 expression level, and FN1 expression level were uniformly potent predictors, with positive weights in all of the three subgroups." (PMID 23460802, 2013). "In addition, the CCL5–SDC4/1 interaction between BTG1+RGS1+ Tcms and tumor cells may promote tumor progression." (PMID 37333982, 2023). "Rgs1 has been previously identified as a critical regulator of the chemotactic activity of different immune cells including myeloid cells, B lymphocyte entrance into, and migration within, lymph nodes, migration and frequency of follicular helper T cells and tumor-infiltrating T cells." (PMID 37153600, 2023). "Additionally, RGS1 gene-silenced NCIN87-DR cell immunization could also strengthen the inhibitive effect of T-mab on tumor growth (tumor size) when compared with that of mice in NCIN87-DR+T-mab group (p < 0.05)." (PMID 37529094, 2022). "Thus, RGS1 gene-silenced NCIN87-DR cell immunization could obviously inhibit tumor growth of Xenograft tumor mice." (PMID 37529094, 2022). "Our approach provided a significant number of genes related to T cell function in the tumor microenvironment, including HSP90AA1, ETS1, CXCR4, RGS1, and FYN, all detected at the gene level." (PMID 39548591, 2024). "Interestingly, RGS1 expression showed a negative correlation with tumor-associated macrophage M2." (PMID 37735297, 2024). "We found that the CCL5 ligand secreted by BTG1+RGS1+ Tcm and HSPA1B+ Tcm cells bound to the SDC4/1 receptor on the surfaces of tumor cells." (PMID 37333982, 2023). "It was found that RGS1 gene silence reduced the proliferation of NCIN87-DR cells and inhibited tumor growth." (PMID 37529094, 2022). "In conclusion, RGS1 gene silence reduced the proliferation of NCIN87-DR cells in vitro and inhibited tumor growth in vivo." (PMID 37529094, 2022). "At the gene level, most tumor-infiltrating MAIT cells expressed CCL4, CCL3, and RGS1, indicating a high response to inflammation." (PMID 33205061, 2020). "Notably, RGS1, CBLB, and FYN were expressed at higher levels, while IFNG was expressed at lower levels across all tumor-infiltrating NK clusters compared to the preinfusion NK clusters." (PMID 40315330, 2025). "Notably, only two genes including regulator of G-protein signaling 1 (RGS1) and CD82 were classified into the Same type for all four MPLCs patients with higher expression in tumor tissues than normal tissues." (PMID 37488117, 2023). "In addition, we also found that RGS1 and CD82 were co-over-expressed by all tumor lesions for all four MPLCs patients." (PMID 37488117, 2023).
tumor (continued). "Fourthly, RGS1 expression in tumour specimen was not determined in this study, and it deserved further investigation of its consistency with blood RGS1 and its correlation with T‐cell exhaustion." (PMID 38081176, 2023). "Fifth, the expression of RGS1 in tumor tissues of Xenograft tumor mice has not been quantified and its correlation with Ki67 has not been analyzed in this study." (PMID 37529094, 2022). "Totally, the silence of RGS1 could reduce the proliferation of NCIN87-DR cells in vitro and inhibited tumor growth in vivo." (PMID 37529094, 2022). "RGS1 gene-silenced NCIN87-DR cell immunization significantly downregulated Ki67 expression in tumor tissues compared with that without RGS1 silence." (PMID 37529094, 2022). "RGS1 gene-silenced NCIN87-DR cell immunization predominantly inhibited tumor growth in Xenograft tumor mouse than that without RGS1 silence (p < 0.05)." (PMID 37529094, 2022). "In addition, there is significant immune infiltration into tumor lesions, and the interaction between BTG1+RGS1+ Tcms and tumor cells via CCL5–SDC4/1 axis may promote tumor progression." (PMID 37333982, 2023). "Interestingly, RGS1 was positively correlated with the abundance of neutrophils, myeloid DCs, and CD8+ T cells in tumors, and RGS1 expression was markedly down-regulated in patients with high tumor immune infiltration." (PMID 35819135, 2022). "Furthermore, qPCR results confirmed the microarray expression data of RGS1 and EEF1A1 in tumor ischemic colorectal tissue samples whereas differential expression of DUSP1, CYR61, SLC6A14 and DUOX2 in tumor ischemic colorectal tissue samples could not be validated." (PMID 26222051, 2015).
cancer (27 papers, 2010 to 2025). A tumor composed of atypical neoplastic, often pleomorphic cells that invade other tissues. "This can be explained by the poor prognostic association between RGS1 and different cancer diseases, supporting the proliferation and invasion of cancer cells." (PMID 37437037, 2023). "A pan-cancer study found that RGS1 was associated with prognosis in multiple tumors, with its high expression leading to the development of a poorer prognosis in ACC, as well as a facilitative effect on T cell exhaustion." (PMID 36899891, 2023). "We also added and compared the expression levels of RGS1 across different cancer stages and found that RGS1 expression was associated with stage in some cancer types, such as RGS1 expression was higher in stages II, III, and IV vs. stage I in STAD." (PMID 34956194, 2021). "Our data support this hypothesis in that the increase in autoreactive B cells following combined CTLA-4 and PD-1 blockade in patients with cancer was associated with elevated proportions of blood Tregs with decreased RGS1 expression, which favors T cell egress from the gut." (PMID 41026527, 2025). "RGS1 expression differences in the TCGA database in a pan-cancer analysis of RGS1 expression differences were first analyzed in this study." (PMID 37735297, 2024). "In patients with advanced cancer or "Dead" survival, the immune cells were depleted and infiltrated less, leading to lower expression of RGS1." (PMID 35879796, 2022). "RGS1 protects normal cells from development and progression by increasing anticancer immunity or inhibiting the transformation of cell phenotypes into cancer." (PMID 37529094, 2022). "In their oligonucleotide microarray study of cancer tissues from 19 patients with early stage and 10 patients with advanced stage, they found that RGS1 expression is elevated in patients with advanced stage cancer, in contrast to our TCGA database analysis." (PMID 35879796, 2022). "In three-cancer single-cell datasets, it was obvious that RGS1 showed positive correlation with 35 genes (up to 0.3~0.8), indicating that consistency of coexpression patterns between these genes." (PMID 34956194, 2021). "In the comparison with Teff cells, RGS1 showed almost the greatest fold change in Pre_exhaust and Tex cells of three cancers with poor prognosis and displayed highly positive correlation with the well-known genes associated with T-cell exhaustion." (PMID 34956194, 2021). "In the differentially expressed genes, RGS1 showed the greatest fold change in Pre_exhaust and exhausted cells of three cancers compared with effector T cells, and high expression of RGS1 was also associated with poor prognosis in various cancers." (PMID 34956194, 2021). "KIF20A and RGS1 genes have been reported to play critical roles in the development and progression of cancer, and promote the proliferation, migration and invasion of cancer cells." (PMID 32467670, 2020). "The other host genes of SNPs in chemotherapy group, RGS1, and RGS11, have also been associated with the etiology and prognosis of cancer." (PMID 21698121, 2011). "In addition, regulator of G‐protein signalling 1 (RGS1) has been recognized as a critical regulator of cancer immunogenicity." (PMID 40673641, 2025). "A correlation of RGS1 with T cell exhaustion has been observed in various cancers, including NSCLC." (PMID 39548591, 2024). "RGS1 is crucial for cancer immune evasion and is upregulated in multiple cancers." (PMID 39400959, 2024). "However, RGS1 knockdown can inhibit tumor growth, migration, and proliferation by promoting cancer cell apoptosis." (PMID 37508372, 2023). "Therefore, targeting RGS1 has excellent potential for adjunct cancer immunotherapy for patients with CC." (PMID 37508372, 2023). "In addition, RGS1 is highly expressed in multiple malignancies and predicts poor prognosis in cancers." (PMID 35879796, 2022).
cancer (continued). "According to these findings, we found that RGS1 is a target to block the proliferation of cancer cells, which may be beneficial to the function of antitumor drugs (such as T-mab)." (PMID 37529094, 2022). "RGS1, as the most upregulated gene in Pre_exhaust and Tex cells, might play key roles in T-cell exhaustion or cancer progress." (PMID 34956194, 2021). "Obviously, regulator of G protein signaling 1 (RGS1) showed the greatest fold change in Tex cells across three cancers and also across different patients, showing the greatest fold change in Pre_exhaust cell in HCC and NSCLC, illustrating its potential roles during T-cell exhaustion." (PMID 34956194, 2021). "However, several studies have shown that RGS1 interacts with other receptors and may play a role in inhibiting cancer cell progression." (PMID 40754247, 2025). "Besides, the Immunoscore (IPS) dataset retrieved from The Cancer Immunome Atlas (TCIA) was used to ascertain if the expression level of RGS1 influences the efficacy of antibody responses against anti-PD-1 and CTLA-4 for a further examination of the connection between RGS1 and immunotherapy reaction." (PMID 37735297, 2024). "However, to date, only a few studies reported the role of RGS1 in cancer cells, and no studies have even involved the association between RGS1 and EMT of cancer cells." (PMID 37529094, 2022). "Therefore, we speculated that RGS1 might be involved in the transformation of EMT into cancer cells." (PMID 37529094, 2022). "Considering the GTP-hydrolysis activity of RGS1 and significantly high mRNA and protein expression in cancer tissues, we speculated that RGS1 potentially mediate the T-cell retention to lead to the persistent antigen stimulation, resulting in T-cell exhaustion." (PMID 34956194, 2021). "Gene differential expression analysis revealed that cancer cell subgroup 1 was characterized by high expression of genes such as TMEFF2, subgroup 2 by high expression of genes such as RGS1, and subgroup 3 by high expression of genes such as CLDN11." (PMID 40843359, 2025). "RGS1 overexpression in CC correlates with increased HPV+ E6 in AC and cervical SCC, contributing to rapid cancer progression." (PMID 37508372, 2023). "Among them, KRT7 was highly expressed in cancer cells, AEBP1 was mainly expressed in fibroblasts, BCL2A1 and RGS1 were both highly expressed in myeloid cells." (PMID 37996875, 2023). "CX3CR1low TEFF highly expressed regulators of G protein signaling (RGS1 and RGS2) that was related to lower infiltration to cancer." (PMID 37080999, 2023). "CD4+CD45RO+ T cells in the lesional blood highly expressed genes relating to cancer progression and CTCL pathogenesis: RGS1, RDH10, HES1, DNAH9, ANK2, and SGK1 16–25." (PMID 34608214, 2021). "In contrast, RGS1 failed to inhibit S1P2- and S1P3-mediated Gα signaling as well as downstream effects, such as enhanced cell migration and cancer-associated gene expression." (PMID 40754247, 2025). "The finding suggested that RGS1 was mainly expressed in immune cells rather than cancer cells, which was consistent with the previous study." (PMID 38081176, 2023).
infection (8 papers, 2013 to 2025). The state of being infected such as from the introduction of a foreign agent such as serum, vaccine, antigenic substance or organism. "(J) The top lineage driver gene, Rgs1, in infected keratinocytes, was ubiquitously expressed in infection-specific Louvain clusters." (PMID 38767331, 2024). "We found that the ferroptosis markers, such as the relative iron and MDA levels were increased by H37Rv infection, and their levels were lower under RGS1-KD treatment." (PMID 39123125, 2024). "This expression profile thus implies that similar to Hobit/Zfp683 gene expression, the induction of Rgs1 expression represents an early event during the local differentiation of CD8+ TRM cells at the site of the infection." (PMID 37153600, 2023). "Previously immunized mice harboring OT-I Rgs1+/+ TRM cells at the site of the infection showed markedly decreased Lm-OVA titers in mLN, spleen, and liver." (PMID 37153600, 2023). "We observed that the proportion of ToxAp:RGS1 conidia reduced after two generations of infection to 30.83% and showed a fitness coefficient of 0.45 after two generations." (PMID 36913579, 2023). "The underrepresentation of the OT-I Rgs1-/- T cells persisted to become even more pronounced during the memory phase (d30 post-infection)." (PMID 37153600, 2023). "Collectively, Rgs1 expression by intestinal CD8+ T cells affects the accumulation of antigen-specific CD8+ T cells in the small intestinal mucosa following i.g. infection with Lm-OVA." (PMID 37153600, 2023). "Rgs1 overexpression strains are however significantly under-represented in the pathogen population after two generation of mixed infections." (PMID 36913579, 2023). "Collectively, these findings reveal that the rapid Rgs1 upregulation in antigen-specific CD8+ T cells represents an early event during local CD8+ TRM cell differentiation at the site of infection." (PMID 37153600, 2023). "The underrepresentation of OT-I Rgs1-/- cells at the site of infection cannot be fully attributed to differences in the proliferative activity of Rgs1+/+vs. Rgs1-/- OT-I cells during this period." (PMID 37153600, 2023). "Transcriptional profile analysis of the 60 putatively Rgs1-repressed effectors during infection demonstrated that they peak in expression at either 48 or 72 hpi." (PMID 36913579, 2023). "The rs2816316 susceptibility allele is located on chromosome 1q31 and maps 8 kb from distal to the 5′ end of RGS1, which is involved in lymphocyte migration and can influence cell trafficking both in immune system development and exogenous infection." (PMID 27043536, 2016). "Western blotting demonstrated that H37Rv infection could significantly enhance RGS1 expression, and RGS1 expression was down-regulated under RGS1-KD treatment." (PMID 39123125, 2024). "This may indicate a higher propensity of intestinal OT-I Rgs1-/- cells to differentiate into SLEC at the site of the infection, which may contribute to the observed preferential disappearance of OT-I Rgs1-/- cells from the small intestinal mucosa." (PMID 37153600, 2023). "The underrepresentation of intestinal OT-I Rgs1-/- cells was also seen following a systemic infection of mice with LCMV-OVA where at day 8 post infection (i.p.)with LCMV-OVA; the OT-I Rgs1-/- cells were present in significantly lower frequencies in the small intestinal IEL and LPL compartment." (PMID 37153600, 2023). "To assess whether Rgs1 is involved in the early expansion of T cells at the site of infection, we first assessed the kinetics of OT-I Rgs1+/+vs. OT-I Rgs1-/- cells early after i.g. infection with Lm-OVA; i." (PMID 37153600, 2023). "Hence, we examined the protective capacity of OT-I Rgs1-/- vs. wild-type OT-I TRM cells upon a local re-infection of the small intestine." (PMID 37153600, 2023).
infection (continued). "Having established that Rgs1 expression is rapidly induced in antigen-specific CD8+ T cells at the site of infection, we next investigated whether Rgs1 expression in antigen-specific CD8+ T cells affects their accumulation during a local immune response against a pathogen." (PMID 37153600, 2023). "Standard spray infections did not reveal any difference in the ability Rgs1 or N-Rgs1 overexpression strains of the fungus." (PMID 36913579, 2023). "Collectively, these findings thus indicate that differential chemotactic migration and mobility of OT-I cells in the presence, or absence, of Rgs1, are unlikely to solely explain the lower frequency of OT-I Rgs1-/- cells in the small intestinal mucosa in mice early after infection with Lm-OVA." (PMID 37153600, 2023). "The observed higher propensity of OT-I Rgs1-/- IEL to undergo apoptosis early (day 6) post-infection with Lm-OVA indicates that absence of Rgs1 may indeed critically regulate the fate decision of antigen-specific CD8+ T cells, particularly, during inflammatory conditions." (PMID 37153600, 2023).
cardiovascular disease (2 papers, 2015 to 2024). "Our study identifies therapeutic targeting of RGS1 to reduce local vascular inflammation as a new rational strategy for the treatment of cardiovascular diseases." (PMID 25782711, 2015).
mental illness (2 papers, 2016 to 2019). "We also tested whether RGS1, which is expressed by microglia, is differentially expressed in the brain samples of mental illness patients, but could not detect significant differences in patients and controls." (PMID 31150013, 2019).
RGS1 also shares sentences with these, for which no sentence is quoted: breast tumor (2 papers); cholangiocarcinoma (2); Crohn disease (2); lung adenocarcinoma (2); rectal adenocarcinoma (2); rheumatoid arthritis (2); stomach cancer (2); systemic lupus erythematosus (2); type 2 diabetes (2); acute respiratory distress syndrome (1); adenocarcinoma (1); adrenocortical carcinoma (1); allergies (1); aortic atherosclerosis (1); Arthritis (1); autism spectrum disorder (1); B cell lymphoma (1); cardiac hypertrophy (1); cell renal cell cancer (1); clear cell renal cell carcinoma (1); depression (1); gastritis (1); hyperlipidemia (1); infectious disease (1); inflammation (1); leishmaniasis (1); lung squamous cell carcinoma (1); metabolic disease (1); myelodysplastic syndrome (1); narcolepsy (1).
A further 19 diseases each share a sentence with RGS1 in 1 paper.